ACKR2 (atypical chemokine receptor 2)
Diseases named in the same sentence as ACKR2 in open-access papers (continued):
Sharing a sentence is not in itself a finding about the gene and the disease.
diabetes (2 papers, 2016 to 2024). "MCP-1, being an overall chemotactic factor, recruits macrophages for immune responses, which along with its receptors (such as CCR2, ACKR1, and ACKR2), significantly impact diseases across different systems like cancer and diabetes." (PMID 39654886, 2024). "Unexpectedly, ACKR2 deletion reduced renal inflammation in diabetes and the ultimate response was a high degree of protection from diabetic nephropathy." (PMID 26798651, 2016). "In human samples diabetes increased the expression of ACKR2 protein in tubule cells, leukocytes, and endothelial cells." (PMID 26798651, 2016). "The finding of such potent renal protection from diabetes by deletion of ACKR2 was contradictory to our expectation, which was that deletion of ACKR2 would exacerbate DN by increasing renal inflammation." (PMID 26798651, 2016). "The results demonstrate a significant interaction between diabetes and ACKR2 protein in the kidney." (PMID 26798651, 2016). "We further observed a tendency for diabetes to increase ACKR2 RNA expression in OVE mouse kidney." (PMID 26798651, 2016). "The effect of diabetes on kidney ACKR2 protein expression was evaluated in human DN and nondiabetic samples using a rat anti-human ACKR2 monoclonal antibody, previously evaluated on human samples." (PMID 26798651, 2016). "The role of ACKR2 has not been examined for a complication of diabetes." (PMID 26798651, 2016). "In summary, we found that deletion of the ACKR2 gene produced a dramatic reduction in albuminuria and renal inflammation in the OVE diabetic mouse without decreasing diabetes." (PMID 26798651, 2016).
diabetic kidney disease (2 papers, 2016 to 2017). Progressive kidney disorder caused by vascular damage to the glomerular capillaries, in patients with diabetes mellitus. "This study demonstrates that the ACKR2 chemokine scavenger receptor has an unexpected important role in the development of diabetic kidney disease." (PMID 26798651, 2016). "In this study, we utilized ACKR2−/− mice to test whether ACKR2 elimination alters progression of diabetic kidney disease." (PMID 26798651, 2016).
epithelial ovarian cancer (2 papers, 2021 to 2025). "DPP4 attenuates C-X-C motif ligand 10 (CXCL10) and atypical chemokine receptor 2 (ACKR2) activity by regulating N-terminal processing, while DPP4 inhibitors may serve as second-line treatment for epithelial ovarian cancer." (PMID 34359286, 2021).
fibrosis (2 papers, 2022 to 2024). the formation of excess fibrous connective tissue in an organ or tissue in a reparative or reactive process. "Bleomycin-induced pulmonary fibrosis increases Ackr2 expression, while CCR4-/- mice, protected from fibrosis, exhibit higher Ackr2 levels." (PMID 39768150, 2024). "In bleomycin-induced IPF in ACKR2–/– mice, it has been confirmed that these mice displayed a reduced pulmonary dysfunction and fibrosis that were related to decreased expression of genes associated with fibrogenesis and Th2/Th17 responses." (PMID 35677043, 2022). "In conclusion, ACKR2 is activated during bleomycin-induced pulmonary fibrosis, and its deletion reduces mortality, lung damage, inflammation, and fibrosis." (PMID 35677043, 2022).
lupus (2 papers, 2024 to 2026). "We next evaluated the effect of the Ackr2 genotype on lupus autoantibody production." (PMID 38799420, 2024). "Additionally, ACKR2 inhibits T‐cell proliferation and the development of tertiary lymphoid structures, but it is not crucial for reducing autoimmune tissue damage in lupus‐susceptible B6lpr mice." (PMID 41532007, 2026). "In conclusion, this study suggests that ACKR2-mediated systemic chemokine clearance may limit formation of tertiary lymphoid tissue, but has no major role in controlling autoimmune activity or inflammatory organ injury including lupus nephritis in lupus-prone B6lpr mice." (PMID 38799420, 2024). "In summary, we show that ACKR2 prevents expansion of T cells and formation of tertiary lymphoid tissue, but is not essential to limit autoimmune tissue injury in lupus-prone B6lpr mice." (PMID 38799420, 2024). "As such, lack of ACKR2 may result in different outcomes in other lupus prone mouse strains than B6lpr mice." (PMID 38799420, 2024). "Our results in the B6lpr mice with SLE and lupus nephritis do not replicate previous findings on the function of ACKR2 in other renal disease models." (PMID 38799420, 2024).
preeclampsia (2 papers, 2022 to 2025). Preeclampsia is a hypertensive disorder of pregnancy that is characterized by new-onset hypertension with proteinuria presenting after 20 weeks of gestation, and depending on mild or severe forms may initially present with severe headache, visual disturbances, and hyperreflexia. "Collectively, hypoxia in the placenta induces downregulation of ACKR2 and CCL2-related inflammation, leading to preeclampsia and probably fetal loss." (PMID 35677043, 2022). "This explanation is consistent with the in vitro discovery of increased ACKR2 expression but decreased CCL2 scavenging in cytotrophoblast membranes separated from preeclampsia placentae." (PMID 35677043, 2022). "Additional research is required to elucidate the role of ACKR2 scavenging in the etiology of preeclampsia and to identify novel treatment approaches targeting the ACKR2 molecular system." (PMID 35677043, 2022). "ACKR2 deficiency promotes cellular apoptosis and elevates CCL2 levels, while increased apoptotic trophoblasts in preeclampsia may enter maternal circulation, triggering systemic inflammation." (PMID 41463301, 2025). "Besides the role of ACKR2 in preeclampsia, it was proposed that levels of ACKR2 expression in the different types of preeclampsia (early-onset preeclampsia, late-onset preeclampsia, and preterm birth) might be a biomarker of the condition’s progress." (PMID 35677043, 2022). "Indeed, it is plausible to infer that optimizing ACKR2 function may help mitigate the excessive inflammatory response seen in preeclampsia." (PMID 35677043, 2022). "ACKR2 mRNA and protein levels in the early-onset preeclampsia and the preterm birth group but not late-onset preeclampsia were significantly reduced compared with normal subjects." (PMID 35677043, 2022). "ACKR2, expressed in non-hematopoietic cells including placental villous trophoblasts, shows significantly reduced mRNA and protein expression in early-onset preeclampsia compared to term deliveries." (PMID 41463301, 2025).
renal fibrosis (2 papers, 2016 to 2024). A final common manifestation of a wide variety of chronic kidney diseases characterized by glomerulosclerosis and tubulointerstitial fibrosis. "Therefore, Ackr2 deficiency did not affect the extent of renal fibrosis in B6lpr mice with lupus nephritis at week 28, being consistent with comparable renal inflammation in WT- and Ackr2-/- B6lpr mice." (PMID 38799420, 2024). "Deletion of the ACKR2 gene in OVE diabetic mice produced a great reduction in albuminuria, accompanied by reduced severity of renal fibrosis, leucocyte infiltration, and inflammatory chemokine gene expression." (PMID 26798651, 2016).
skin cancer (2 papers, 2022 to 2025). "In contrast, transgenic expression of ACKR2 in keratinocytes reduced inflammation and decreased the susceptibility of mice to skin tumors." (PMID 35677043, 2022). "However, transgenic expression of ACKR2 in keratinocytes reduced inflammation and lowered the risk of skin tumours." (PMID 40852716, 2025).
thyroid cancer (2 papers, 2017 to 2024). "Down-regulation of D6/ACKR2 expression by miR-146a warrants to thyroid cancer cells the property to recruit inflammatory cells in vitro and in vivo." (PMID 28740576, 2017). "To study the role of D6/ACKR2 in thyroid cancer, we infected the BHT101 cells with a lentivirus carrying the human D6/ACKR2 cDNA fused in frame with a FLAG sequence." (PMID 28740576, 2017). "Thus, thyroid carcinomas maintain low D6/ACKR2 levels to sustain chemokine trafficking inside tumor microenvironment and to ensure tumor progression driven by the pro-oncogenic activity of recruited inflammatory cells." (PMID 28740576, 2017). "All together these findings indicate that D6/ACKR2 is a target of the miR146a and that restoring its expression in thyroid cancer cell lines decreased macrophage chemotaxis both in vitro and in vivo." (PMID 28740576, 2017). "The chemokine scavenger receptor D6/ACKR2 is a target of miR-146a in ATC cells: human specimens from primary ATCs show a low expression of D6/ACKR2 compared to normal thyroid tissues, suggesting an antioncogenic role for this receptor in thyroid cancer." (PMID 39519020, 2024).
abdominal aortic aneurysm (1 paper, 2023). Enlargement and ballooning of the vessel that supplies arterial blood to the abdomen, pelvis and legs. "For example, several (5/39) of the significant genes (including LPL, IFI44L, ACKR2, HBA1, and HBA2) have also been found to be differently expressed in abdominal aortic aneurysms." (PMID 36836499, 2023).
Allergy (1 paper, 2016). An allergy is an immune response or reaction to substances that are usually not harmful. "Here, we provide a summary of the data on the role of ACKR2 expressed by lymphatics, indicating an essential role for this ACKRs in the regulation of the inflammation and the immune response in different pathological conditions, including infection, allergy, and cancer." (PMID 28123388, 2016).
alveolitis (1 paper, 2024). "Of note, next to peribronchal T cell infiltrates no other parenchymal lung injury, e.g. alveolitis or interstitial fibrosis could be detected in WT- or Ackr2-/- B6lpr mice." (PMID 38799420, 2024).
Arthritis (1 paper, 2015). Inflammation of a joint. "There was in fact a small increase in EAE score when Ackr2-deficient mice on a DBA/1j background were compared with WT DBA/1j mice, and Ackr2-deficient DBA/1j mice also developed worse arthritis than WT animals during CIA." (PMID 25348934, 2015). "To investigate this directly, we examined the impact of Ackr2 deficiency on the development of anti-collagen antibody-induced arthritis." (PMID 25348934, 2015). "Thus, ACKR2 is locally upregulated in response to the development of inflammation in the mouse joint, controls the levels of inflammatory CC chemokines in the diseased tissue and suppresses the clinical symptoms of arthritis." (PMID 25348934, 2015). "In contrast to previous observations in the EAE model, the absence of Ackr2 resulted in a statistically significant increase in the clinical symptoms of arthritis, and a substantial increase (P<0.05) in the cumulative clinical score of Ackr2-deficient mice (24.2±3.6, mean±s.d)." (PMID 25348934, 2015).
arthropathy (1 paper, 2017). Any disorder of the joints. "Some patients displayed extremely elevated levels of ACKR2 expression and, overall, there was an almost five log spread in ACKR2 levels when data from healthy controls and all three arthropathy groups were pooled." (PMID 28486662, 2017). "Surprisingly in the arthropathy groups studied (as well as in psoriatic patients) there is no apparent correlation between peripheral blood ACKR2 expression and disease severity (available at Rheumatology Online)." (PMID 28486662, 2017).
asthma (1 paper, 2022). "As a result, ACKR2 possesses conflicting effects on asthma in which it has anti-inflammatory properties while promoting reactions in the airways." (PMID 35677043, 2022). "In asthma, like other pulmonary diseases including COPD and IPF, the expression of ACKR2 has also been dysregulated." (PMID 35677043, 2022).
bladder cancer (1 paper, 2024). "On the TCGA bladder cancer dataset, RTCpredictor re-identified three out of six known read-throughs (ACKR2-KRBOX1, CHCHD10-VPREB3 and SLC2A11-MIF)." (PMID 38796690, 2024).
breast tumor (1 paper, 2022). "ACKR2-induced breast tumor inhibition results mainly from decoying inflammatory chemokines (e.g., CCL2), inhibiting vascular density, and suppressing tumor-associated macrophage infiltration." (PMID 35677043, 2022).
cervical squamous cell carcinoma (1 paper, 2022). A squamous cell carcinoma arising from the cervical epithelium. "Analyzing the association of ACKR2 with the prognosis of cervical squamous cell carcinoma (CSCC) showed that ACKR2 expression is reduced in CSCC compared to the normal cervix, and its expression was negatively related to tumor size." (PMID 35677043, 2022).
colorectal adenoma (1 paper, 2020). An adenoma that arises from the colon or rectum. "We aimed at transcriptional analysis (RTqPCR) of ACKR2 and ACKR4 expression in colorectal adenoma-adenocarcinoma sequence in paired normal-neoplastic tissues from 96 polyps and 51 cancers." (PMID 33374792, 2020).
corneal disease (1 paper, 2022). "Interestingly, despite significant corneal disease, ACKR2-/- mice did not develop hypopyon with 6.0 x 106 pfu HSV-1 unlike WT mice (7 of 10 mice) (white arrowheads)." (PMID 36518752, 2022).
Corneal opacity (1 paper, 2022). A reduction of corneal clarity. "With both doses, ACKR2-/- and WT mice developed significant corneal opacity within 3 days post infection (p.i.)." (PMID 36518752, 2022). "With 5.4 x 105 pfu HSV-1, corneal opacity in the WT mice rapidly resolved at 1week p.i. with near complete restoration of corneal clarity, whereas in ACKR2-/- mice, HSK was significantly prolonged with higher corneal opacity scores at day 7 and 14 p.i.." (PMID 36518752, 2022).
COVID-19 (1 paper, 2025). A disease caused by infection with severe acute respiratory syndrome coronavirus 2. "The key finding from our inflammatory network analysis of COVID-19 samples is that ACKR2 plays a vital role, acting as a crucial broker between the RNA and protein inflammation networks." (PMID 40362649, 2025). "In particular, molecular interplay between ACKR2 and its neighborhood plays a key role in the inflammatory mechanism involved in COVID-19 severity." (PMID 40362649, 2025). "Our multi-omics data analysis revealed a novel COVID-19 marker ACKR2 that acts as a crucial broker between RNA and protein inflammation networks." (PMID 40362649, 2025). "Thus, ACKR2 plays a key role in the inflammatory gene networks of COVID-19 samples, and can be considered a crucial COVID-19 severity marker." (PMID 40362649, 2025). "Our large-scale RNA/protein expression data analysis reveals that the atypical chemokine receptor 2 (ACKR2) acts as a key broker linking RNA and protein inflammation networks to induce COVID-19 critical severity." (PMID 40362649, 2025). "Thus, uncovering novel treatment approaches targeting the molecular system of ACKR2, S100A8, and S100A9 for COVID-19 is a future research step in our study." (PMID 40362649, 2025). "Furthermore, recovery from severe SARS-CoV-2 infection involves an expansion of ACKR2-expressing ILC2 cells, underscoring the importance of targeting this subset to promote lung recovery in COVID-19 and other related diseases." (PMID 40362649, 2025).
dysplasia (1 paper, 2020). A usually neoplastic transformation of the cell, associated with altered architectural tissue patterns. "Neither ACKR2 nor ACKR4 expression ratios (normal-to-polyp) differed significantly depending on dysplasia grade." (PMID 33374792, 2020).
glioblastoma (1 paper, 2019). The most malignant astrocytic tumor (WHO grade IV). "In the glioblastoma cells we are studying here, though, we do not deem it likely that CXCL14 functions are mediated by ACKR2, as the expression of its mRNA, that we measured by qRTPCR, was undetectable in both U87MG and LN229 cells (not shown)." (PMID 31117166, 2019). "Moreover, as for GPR85, our SAGE data in glioblastoma samples and an RNA-seq analysis on GBM stem-like cells we recently performed, showed only a barely detectable level of ACKR2 mRNA expression in tumor samples and data not shown." (PMID 31117166, 2019).
glomerulonephritis (1 paper, 2022). A renal disorder characterized by damage in the glomeruli. "The function of ACKR2 was also examined in another inflammatory condition, i.e., glomerulonephritis." (PMID 35677043, 2022).
Hypertension (1 paper, 2022). The presence of chronic increased pressure in the systemic arterial system. "Therefore, it is needed to explore the role of ACKR2 in hypertension and its association with dysregulation of other chemokine receptors and inflammatory mediators." (PMID 35677043, 2022). "However, it is presented in an oral presentation abstract that ACKR2-deficient mice had lower T-cell content and lower CCR5 expression in the perivascular adipose tissue, which is linked to hypertension." (PMID 35677043, 2022).
influenza (1 paper, 2021). An acute viral infection of the respiratory tract, occurring in isolated cases, in epidemics, or in pandemics; it is caused by serologically different strains of viruses (influenzaviruses) designated A, B, and C, has a 3-day incubation period, and usually lasts for 3 to 10 days. "Akin with that, mice lacking the CCL5 scavenger Atypical Chemokine Receptor 2 (ACKR2) present increased CCL5 levels, CCR5+CD4+ lymphocyte recruitment to the airways and augmented levels of IgA in the BALF during influenza." (PMID 35126379, 2021).
kidney injury (1 paper, 2024). Trauma to the kidney. "Thus, Ackr2-dependent chemokine clearance is apparently essential in down-regulating renal chemokine levels and inflammatory activity during the regeneration phase which follows severe but temporarily limited kidney injury." (PMID 38799420, 2024).
lupus nephritis (1 paper, 2024). Glomerulonephritis in the context of systemic lupus erythematosus. "Thus, we hypothesized that Ackr2 deficiency might enhance renal leukocyte recruitment into inflamed kidneys and lungs of B6lpr mice with lupus nephritis, leading to more severe organ inflammation and injury." (PMID 38799420, 2024). "Thus, Ackr2 deficiency in B6lpr mice resulted in increased tubulointerstitial T and B cell infiltration, but did not affect neutrophil or macrophage accumulation in kidneys with lupus nephritis." (PMID 38799420, 2024). "The potential ability of ACKR2 to limit renal inflammation and injury in lupus nephritis of B6lpr mice was first explored in vitro using glomeruli and tubulointerstitial tissue isolated from WT- and Ackr2-/- B6lpr mice." (PMID 38799420, 2024). "Together, this data suggested a potential anti-inflammatory effect of Ackr2 in lupus nephritis of B6lpr mice by reducing local chemokine production in kidneys." (PMID 38799420, 2024). "To characterize a potential nephroprotective effect of Ackr2 in B6lpr mice with lupus nephritis we first evaluated excretory kidney function in female WT- and Ackr2-/- B6lpr mice at the age of 28 weeks." (PMID 38799420, 2024). "Currently, it remains unknown whether ACKR2 could also protect from autoimmune injury such as lupus nephritis, by limiting local chemokine production and inflammation." (PMID 38799420, 2024). "However, the glomerular injury was comparable in WT- and Ackr2-/- B6lpr mice, as demonstrated by similar activity and chronicity indices for lupus nephritis after morphometric assessment." (PMID 38799420, 2024). "Furthermore, mRNA expression analysis demonstrated that renal Ackr2 expression was induced by 4.3-fold in female WT-B6lpr mice with lupus nephritis at week 28 of age compared to age-matched healthy B6 WT controls without the lpr mutation." (PMID 38799420, 2024). "However, all analyzed inflammatory mediators were similarly expressed in WT- and Ackr2-/- B6lpr mice with lupus nephritis." (PMID 38799420, 2024). "Thus, B6lpr mice developed lupus nephritis with mild glomerular and tubular injury until week 28, but impaired tubulointerstitial chemokine scavenging in Ackr2-deficient mice did not result in more severe renal injury." (PMID 38799420, 2024). "However, our data do not rule out a potential protective role of ACKR2 in more advanced lupus nephritis with more severe inflammatory kidney injury, similar to our previous findings in the nephrotoxic serum nephritis model of immune complex-mediated glomerulonephritis." (PMID 38799420, 2024).